SPATC1 (spermatogenesis and centriole associated 1)
Synonyms: SPATA15; MGC61633; SPERIOLIN
Tractability: No criterion of Open Targets' tractability assessment is met for any kind of drug.
Gene: Protein-coding gene on chromosome 8 (144,012,280 to 144,047,114, forward strand). Ensembl gene ENSG00000186583.
Subcellular location: Cytoplasm; Cytoplasm, cytoskeleton, microtubule organizing center, centrosome
Gene Ontology:
Cellular component: centrosome; cytoplasm
Genetic constraint (gnomAD): Loss-of-function variants: 37 observed, 37.97 expected, observed/expected ratio (o/e) 0.97, 90% interval 0.75 to 1.28. The upper end of that interval is the gene's LOEUF score, 1.28, which puts it in group 5 of 6, group 1 being the genes least tolerant of losing a copy. Missense variants: 779 observed, 799.65 expected, observed/expected ratio (o/e) 0.97, 90% interval 0.92 to 1.03. Synonymous variants: 361 observed, 356.23 expected, observed/expected ratio (o/e) 1.01, 90% interval 0.93 to 1.11.
Homologues: Orthologues: chimpanzee SPATC1 (96% identical), macaque SPATC1 (91% identical), rabbit SPATC1 (58% identical), pig SPATC1 (57% identical), mouse Spatc1 (54% identical), rat Spatc1 (54% identical), dog SPATC1 (45% identical). Paralogues in human: SPATC1L (19% identical).
Diseases named in the same sentence as SPATC1 in open-access papers:
SPATC1 is named in the same sentence as 3 diseases in open-access papers, as found by Europe PMC text mining. Sharing a sentence is not in itself a finding about the gene and the disease. The quoted sentences say what the papers report.
cancer (1 paper, 2020). A tumor composed of atypical neoplastic, often pleomorphic cells that invade other tissues. "Taking all these data into account, we identified the following candidates as potential causes of CA in human cancer: gain of function of CEP19, CEP72, CTNNB1, PTK2, NDRG1, SPATC1, TBCCD1; and loss of function of CEP76, MCPH1, NEURL4, NPM1." (PMID 32681070, 2020).
SPATC1 also shares sentences with these, for which no sentence is quoted: breast carcinoma (1 paper); tumor (1).